CXCL11 (C-X-C motif chemokine ligand 11)
Diseases named in the same sentence as CXCL11 in open-access papers (continued):
Sharing a sentence is not in itself a finding about the gene and the disease.
infection (continued). "We found that interferon-stimulated genes, crucial for restricting respiratory virus replication early after infection, such as CXCL10, CXCL9, CXCL11, OAS1, OASL, and ISG15, were significantly upregulated in PCLS 72 h post-infection." (PMID 41239423, 2025). "For example, TYROBP, CCR7, CXCL10, and CXCL11 emerged as top DEGs in both infected and bystander cells in ADE compared to conventional infection." (PMID 39902963, 2025). "As further verification, when we reviewed the list of genes identified from IPA, we found that CXCL11 was found at both 24- and 48-hours post-SARS-CoV-1-infection." (PMID 39874350, 2025). "Beyond CXCL5, our machine-learning approach highlighted several other novel candidates: PDGF-B, Galectin-1, CXCL11, ANGPT1, EGF, TIE2, MCP-2, and NOS3 that each outperformed CXCL5 in discriminating a dormant infection from uninfected joint replacements." (PMID 41387890, 2025). "In particular, the gamma interferon (IFN- γ) inducible chemokines CXCL9, CXCL10, and CXCL11, and their receptor CXCR3, are involved in T cell and macrophage recruitment to the site of infection." (PMID 39301034, 2024). "Chemokines (CCL2, CCL3L1, CCL4, CXCL9, CXCL10, CXCL11, and XCL1) were also significantly upregulated after infection." (PMID 38698849, 2024). "We examined secreted protein levels of IFN-β, CXCL10, CXCL11, CCL5, and IDO in two male and two female primary HLMVEC donors at 48 and 60 h post infection." (PMID 37766212, 2023). "Infection by all three viruses resulted in similar levels of secreted protein levels of CXCL10, CXCL11, and IFN-β." (PMID 37766212, 2023). "The combination treatment with both TMAO and CFT073 had significant additive effects on the release of CXCL11 and CCL20 and synergistic effects on the release of IL-8, CXCL1, and CXCL6 compared to CFT073 infection alone." (PMID 37111409, 2023). "We found three genes that were commonly activated with infection with SCV2 at both 12 and 24 hpi (DUSP1, HES1, KLF2) and some non-congruent genes at 12 hpi (CCL5, ZBP1, NRXN2, STAB1, SLC25A47, CXCL11) and 24 hpi (FOXA2, RHOB)." (PMID 37504520, 2023). "Infection also resulted in the increased expression of CXCL10 and CXCL11 by multiple cell subsets, including goblet 2 cells." (PMID 35038898, 2022). "Analysis of cytokine and chemokines in serum showed a characteristic peak in IL-6, CCL2, CXCL10, and CXCL11 production at day 1 after virus inoculation as also described by others for H5N1 and pH1N1 infection." (PMID 33671829, 2021). "We again assessed changes in host gene expression by RNA-sequencing, and observed a reduction of mRNA levels of various genes induced by the infection, including the cytokines CXCL10 and CXCL11." (PMID 33585804, 2021). "Regarding CXCL11, GSK690693 (4.82-fold reduction) and JNK-IN-8 (2.72-fold reduction) each significantly reduced CXCL11 induction in response to infection as compared to infected cells treated with vehicle alone." (PMID 34205098, 2021). "Nevertheless, MIG/CXCL9, IP-10/CXCL10, I-TAC/CXCL11, BLC/CXCL13 and JE/MCP-5/CCL2 detected in kidney of C3H-HeJ mice at 24h post infection was also detected in serum/blood cells in our study." (PMID 34249775, 2021). "Here, we corroborate these findings in Calu-3 cells using an unbiased genome-wide methodology showing that antiviral cytokines (IFNL1-3, IFNB1, CCL5, CXCL11 and IL6) are restricted in translation at 24 h post infection." (PMID 33806254, 2021). "We used qPCR to validate the SARS‐CoV‐2 infection‐dependent upregulation of the IFN‐γ target genes CXCL11 and IFIT3, as well as KRT20 and ACE2 and indeed confirmed an upregulation of these genes upon infection." (PMID 33544398, 2021). "Accordingly, we analyzed the expression of the chemokines CXCL9, CXCL10, and CXCL11 in unvaccinated and vaccinated mice of the strains C57BL/6, IL-23p19−/−, and IL-17A−/− after infection with Mtb via quantitative real-time RT-PCR analysis." (PMID 34351501, 2021).
infection (continued). "Changes in gene expression in the brains of infected animals is minimal at 2- and 4-days post infection with moderate increases in Interferon-inducible CXCL10, CXCL11, B2m, and STAT1, as well as pro-inflammatory TNF, IL-1b and C3." (PMID 32133008, 2020). "DC isolated early after infection of pigs with either of the two CSFV strains showed prominent upregulation of CCL5, CXCL9, CXCL10, CXCL11, and XCL1, as well as of the cytokines TNFSF13B, IL6, IL7, IL12B, IL15, IL27." (PMID 32733474, 2020). "CXCR3 and its ligands, the IFN-γ-inducible C-X-C chemokines CXCL9, CXCL10, and CXCL11, are important for migration of activated CD4+ Th1 cells to inflamed tissues and sites of infection." (PMID 30915078, 2019). "Interestingly, and as observed after infection of mice with H. pylori, the expression of the chemokines CXCL9 and CXCL10 was strongly reduced in BCG-infected BATF3-deficient compared to WT mice, whereas CXCL11 expression was unaffected by the BCG infection or the mouse genotype." (PMID 31188899, 2019). "In particular, the levels of I-TAC (CXCL11), IP-10 (CXCL10), MIG (CXCL9), and MCP-3 (CCL7) increased nearly 6-fold upon infection." (PMID 30467502, 2018). "We found mRNAs of the type 1 chemokine ligands and their receptors (CCL4, CCL5, CCR5, CXCL9, CXCL10, CXCL11 and CXCR3) were increased at 21–28 days post-infection compared to uninfected controls." (PMID 28103263, 2017). "Upon TBwt infection, several type II ISGs (CXCL9, CXCL10, CXCL11 and IDO) exhibited varying degrees of activation at 24 h post infection in accordance with previous reports." (PMID 27387064, 2016). "Among these, some became upregulated during the early stage of infection (day 4) CCL7, CXCL11, IL1R1 (cytokine receptor) and IL15RA, and others became upregulated during the late stage of infection (day 7): IL2RA, CSF2RB and others." (PMID 27595844, 2016). "Our data clearly show an increased expression of a set of chemokines (CCL20, CCL5, CXCL1, CXCL10, CXCL11, CCL25) normally involved in H. pylori gastritis at both 6 and 18 weeks of infection in mice, which decreased after curcumin treatment." (PMID 25569625, 2015). "With increased time of infection, the expression of M1 macrophage-related markers, including CD86, CXCL11, and TNF-α decreased, while the expression of M2 macrophage-related markers including CD206, CCL17 and IL-10 gradually increased." (PMID 26091535, 2015). "Infection with MOPV induced the massive synthesis of CXCL10 and 11 mRNA in DC, whereas only modest levels of CXCL11 mRNA were detected in response to LASV stimulation." (PMID 24421914, 2014). "An important number of chemokines were strongly up- or down-regulated as a consequence of the infection, including up-regulation of CK3, CK10, CK12 and CXCL11_L1, and down-regulation of CK9 and CXCL14." (PMID 25338079, 2014). "By contrast, significant, but modest, increases in mRNA production in response to infection were observed only for CXCL10 and CXCL11 in LASV-infected MP." (PMID 24421914, 2014). "In these experiments we transduced pLEC with increasing doses of CXCR7 adenovirus, harvested cells at 20 hours post-infection and performed quantitative RT-PCR analysis for mRNA expression of CXCR7, SDF-1/CXCL12 and ITAC/CXCL11." (PMID 23894550, 2013). "While Cxcl9, Cxcl10 and Cxcl11 were upregulated, CXCR3 was downregulated post PCN033 infection." (PMID 41295668, 2025). "A nine-analyte synovial panel consisting of PDGF-B, CXCL5, CXCL11, MCP-2 (CCL8), ANGPT1, TIE2, EGF, NOS3, and Gal-1 distinguished dormant infection from truly aseptic cases with 100% specificity and positive predictive value (sensitivity 22%, negative predictive value 74%)." (PMID 41387890, 2025). "Moreover, infection with SFV/IFNγ and SFV/TNFα upregulated the amount of IL-6, CCL4 and CXCL11 (p < 0.05)." (PMID 40547518, 2025).
infection (continued). "One re-implantation originally labeled indeterminate by clustering was reevaluated against the nine-marker panel and expressed eight of nine dormant-infection proteins (89%, PDGF-B, Gal-1, CXCL11, ANGPT1, EGF, TIE2, MCP-2, and NOS3) prompting its reassignment as a dormant infection." (PMID 41387890, 2025). "Other proinflammatory cytokines that were moderately induced by USUV infection include LIF (member of the IL-6 superfamily), macrophage colony-stimulating factor, CXCL11, and granulocyte colony-stimulating factor, found to be increased on day 6 p.i. in comparison to the mock control." (PMID 39907280, 2025). "In addition, several members of the chemokine family of GPCRs have been observed to be upregulated in Calu-3 cells upon infection, including, among others, CXCL10, CXCL11 and CCL2." (PMID 38786015, 2024). "The DEGs involved in cytokine signaling were upregulated following infection with RHDV2 and included inflammatory cytokines such as IL1α, IL-6, and IL-8, and chemokines such as CCL2, CXCL9, and CXCL11, which were significantly upregulated compared with the non-infected rabbits." (PMID 38675838, 2024). "With IFNγ blockade, genes in cluster 2, including IL18R1, IDO1, CXCL11, CD274 (PD-L1), and PTPN2, were similarly expressed at day 3 post-infection but were more highly expressed at day 7 compared to controls and had increased expression over the day 3 timepoint." (PMID 38950078, 2024). "Similarly, the expression levels of pro-inflammatory response factors (IL-6, TNF-α, CXCL10, CCL7, CXCL11, and CCL2) were significantly decreased at 6 dpi, as compared to virulent WT infection." (PMID 37623322, 2023). "Serving as chemokines, CXCL9, CXCL10, and CXCL11 attract the cells with their cognate receptor CXCR3, including neutrophils, monocytes/macrophages, dendritic cells, T cells, and NK cells, to the site of infection." (PMID 37214455, 2023). "However, at 30 days post-infection, TNF-α, IL-6, KC, CCL3, CCL2, CCL20, CXCL11, CCL11), CCL27, CXCL5, CXCL12 and CCL5 were all significantly higher in the BAL fluid of Duox1 KO compared to WT mice." (PMID 36936954, 2023). "Levels of 3 mediators, CXCL11, CCL19, and IL-21, were higher in patients whose symptoms resolved after antibiotic therapy, implying that they might play a protective role in the infection and contribute to symptom resolution." (PMID 37209716, 2023). "Data on gene-fold change for IFNB1, CCL5, CXCL11, CXCL10, and IDO1 after experimental infection of HLMVEC by pathogenic (ANDV, HTNV) and nonpathogenic (PHV) viruses were recorded at seven timepoints t = 0, 12, 24, 36, 48, 60, 72 hpi." (PMID 37766212, 2023). "At 48 hpi, when we compared mRNA upregulation level to protein concentration for analysed genes, we observed that MRU25010-30 infection did not induce an upregulation of protein despite a strong upregulation of their mRNA levels, except for CXCL11." (PMID 37306630, 2023). "Finally, a high number of pro-inflammatory cytokines were up-regulated upon infection, such as CXCL10, CCL5, CXCL11, TNF, CCL3, CXCL8, and IL6." (PMID 35893684, 2022). "However, a number of genes involved in antiviral defense, inflammatory response, and IFN pathways (i.e., CXCL10, CXCL11, IFIT1, etc.)were commonly upregulated in infected Vero E6 cells and HBECs at later stages of infection." (PMID 35604092, 2022). "Indeed, cytokine profiling revealed a vaccine dose-dependent reduction of infection-induced inflammatory C-X-C motif chemokine ligand 10 (CXCL10) and 11 (CXCL11) in both serum and BAL compared with non-vaccinated controls." (PMID 35479095, 2022). "Furthermore, the top six DEGs, including CSF3, CCL2, CCL7, IL6, CXCL11, and CXCL10, were all upregulated after infection at P3." (PMID 34026883, 2021). "Infection with either virus led to enhanced expression of the inflammatory chemokines CCL5, CXCL10 and CXCL11, whereas mRNA expression levels of IL-6, IL-12 and IL-15 were only increased in MAYV-infected cells." (PMID 33799906, 2021).
infection (continued). "The expression of Cxcl10 and Cxcl11 was maximal in both groups on day 21 after infection with Mtb, after which it decreased slowly and was not significantly different at any time point." (PMID 33375150, 2020). "Furthermore, Ad14p1 infection of the bronchial epithelial cells resulted in increased expression of IL-6 and the chemoattractant chemokines CXCL10 (IP-10) and CXCL11 compared to infection with Ad5." (PMID 32486177, 2020). "CXCL9, CXCL10, and CXCL11 are chemokines which are able to induce chemotaxis in CD4+ Type-1 helper (Th1) and CD8+ cytotoxic lymphocytes as well as in natural killer cells and natural killer T cells, directing them to sites of infection and inflammation." (PMID 32328494, 2020). "While the expression of Cxcl10 and Cxcl11 in C57BL/6 and IL-6−/− mice was similar, it was significantly increased for Cxcl9 in IL-6−/− mice on day 14 and tended to remain higher compared to wild type animals in the further course of infection." (PMID 33375150, 2020). "CXCR3 and its ligands, CXCL9, CXCL10, and CXCL11, play a pivotal role in the regulation of inflammatory and infectious diseases, in which CXCR3-bearing effector leukocytes are recruited to the sites of inflammation or infection." (PMID 27068264, 2016). "However, very shortly after infection (3 days after infection), during the incubation period, CXCL10 and CXCL11 mRNA levels were found to be higher in the PBMC of the monkeys that subsequently survived the acute infection than in the PBMC of monkeys that died." (PMID 24421914, 2014). "However, upon infection with the Sendai virus (SeV), the cells exhibited increased expression of IFN and chemokine genes (IFNB1, IL29, IL28A, IL28B and CXCL11) and interferon-stimulated genes (DDX58, IFIH1, DHX58, IFIT1-3, and OASL)." (PMID 20661427, 2010). "Moreover, the levels of infection-induced CXCL10 and CXCL11 were reduced." (PMID 35479095, 2022). "The CXCL9, CXCL10, CXCL11/CXCR3 axis and TNFSF13B play a role in both these recruitment and activation processes, responsible for attracting Th1 cells, cytotoxic lymphocytes and natural killer cells to the site of the infection, and related to B-cell activation, respectively." (PMID 34276658, 2021). "A positive correlation between MIG/CXCL9, IP-10/CXCL10, I-TAC/CXCL11 and MIP-3β/CCL19 and mononuclear cell infiltrates was also observed in previous studies on TBE patients, confirming their potential involvement in lymphocyte extravasation to the site of infection during TBE." (PMID 34277474, 2021). "Prior to infection, investigation of the expression of key macrophage differentiation markers indicated that (unstimulated) iPSDMs expressed low to very low levels (0.1–5 counts per million (c.p.m.)) of M1 markers (CXCL10, CXCL11 and TAP1) and also modest levels (10–1,000 c.p.m)." (PMID 28440293, 2017). "The genes with strongest induction included chemokines (e.g. CXCL11, 84-fold; CXCL10, 18-fold; CXCL9, 9-fold; CCL2, 9-fold) and cytokines (e.g. IL6, 54-fold; IL12B, 10-fold; IL1B, 9-fold;) etc. consistent with the infection of host phagocytes with Mtb reported earlier by us." (PMID 28880895, 2017). "Although most chemokines/cytokines did not change or remained undetectable during stable infection on days 8 and 12, CXCL9, CXCL10, CXCL11, and IFN-λ1 were increasingly induced at both time points post infection." (PMID 39980752, 2025). "There was significant induction of bronchial IFN-γ, CXCL11/ITAC, CXCL10/IP10, IL-15, IL-10, TNFα and IL-5 during infection in allergic asthmatics (all P < 0.05), but not in healthy controls." (PMID 28373098, 2017). "The induction of the chemokine genes IP-10 (CXCL10) and I-Tac (CXCL11) and of the proinflammatory cytokine gene IL-6 was observed in a genome wide mRNA microarray analysis at 48 h post HAdV-B14p1 infection, but not in HAdV-C5 infected control cultures." (PMID 26168049, 2015).
infection (continued). "In another study in cynomolgus macaques, increases in the synthesis of CXCL-10 and CXCL11 (I-TAC) mRNA were reported in PBMC and lymph nodes, regardless of the outcome of infection." (PMID 24421914, 2014). "On day 7 p.i., in addition to chemokines upregulated on day 3 p.i., lethal infection further induced higher expression of CCL2, CCL6, CCL11, CCL19, CCR7, CXCR1, and CXCL11 compared to nonlethal infection." (PMID 23526993, 2013). "Interestingly, in contrast to our previous studies, there was no vaccine-mediated reduction in the local levels of infection-induced CXCL10 and CXCL11 levels in BAL fluid in any of the treated groups." (PMID 41390777, 2025). "Interestingly, while SIV infection significantly increased CXCL10 and CXCL11 in the hippocampus, it did not increase CCL2 in this area, suggesting regionally specific responses to infection." (PMID 35494221, 2022). "Although specific CD8+ T cells infected expressed higher levels of CXCR3 on cell surface, CD8+ T-cells from the immunized group had a higher migration index compared to specific CD8+ T cells generated only by infection, after the ex vivo stimulation with CXCL9 and CXCL10, but not with CXCL11." (PMID 31356587, 2019). "Additionally, quantitative realtime PCR was performed to validate RNA-seq data and the transcript levels of cytokines/chemokines, such as CXCL10, CXCL11, IFN-γ, TNF-α and IL-24, were all up-regulated upon H5N1 and H5N8 infection (data not shown)." (PMID 26576844, 2015). "Vascular sequestration during a time of local neutrophil depletion helps explain the increased CXCL5, CXCL11, and MCP-2 levels, lack of systemic acute phase reactant expression, and continued monocyte and T-cell activity previously shown to be indicative of dormant infection." (PMID 41387890, 2025).